SUV39H1 (SUV39H1 histone lysine methyltransferase)
Diseases named in the same sentence as SUV39H1 in open-access papers (continued):
Sharing a sentence is not in itself a finding about the gene and the disease.
leukemia (10 papers, 2013 to 2025). A malignant (clonal) hematologic disorder, involving hematopoietic stem cells and characterized by the presence of primitive or atypical myeloid or lymphoid cells in the bone marrow and the blood. "The underlying molecular mechanism mediated by the Suv39h1 in tumor suppression may provide a potential novel therapeutic targeting strategy for MLL-rearranged leukemia." (PMID 33037410, 2020). "The more effective elongation or stabilization of telomeres in c-Myc-driven myeloid leukemias by ALT mechanism may prevent telomere shortening and the induction of CIN in Suv39h1-deficient leukemias." (PMID 24202323, 2013). "SUV39H1 is down-regulated in a variety of leukemia, and knockdown of SUV39H1 leads to an increase in the number of leukemia stem cells (LSCs) and accelerates disease progression." (PMID 38650654, 2024). "It has been found that SUV39H-deficient mice develop B-cell lymphomas with increased frequencies, and SUV39H1 was observed to be downregulated in many leukemias." (PMID 34357075, 2021). "The protective effect of SUV39H1 in leukemia was validated in mouse models using SUV39H1 overexpression or knockdown and the data provided a direct link between SUV39H1 and AML via the silencing of HOXB13 and SIC1." (PMID 34357075, 2021). "We found that SUV39H1 was down-regulated in a variety of leukemias, including MLL-r AML, as compared with normal individuals." (PMID 33037410, 2020). "Increased Suv39h1 expression led to the inactivation of Hoxb13 and Six1, as well as reversion of Hoxa9/Meis1 downstream target genes, which in turn decelerated leukemia progression." (PMID 33037410, 2020). "In the present study, we provide insight into the significance of Suv39h1 in regulating MLL-r leukemia and LSCs." (PMID 33037410, 2020). "Considering the crucial role of LSC in the initiation and maintenance of leukemia, we further analyzed the effect of Suv39h1 on LSCs in MA9 AML mouse model." (PMID 33037410, 2020). "MA9 leukemia cells isolated from quaternary recipients (P3 MA9 cells) that were infected with Suv39h1-overexpression lentivirus have been stably passaged for three times." (PMID 33037410, 2020). "SUV39H1 expression was significantly lower in a variety of leukemias, including the MLL-r AML, when compared with its expression in granulocyte-monocyte progenitor cells (GMPs) or with the nearest normal counterpart, as recently published study." (PMID 33037410, 2020). "In consistent with this, our observation of the role of Suv39h1 in suppression of MLL-AF9 leukemia progression were in agreement with recent publication which reported a suppressive role of Setdb1 in MLL-fusion induced AML." (PMID 33037410, 2020). "Microarray analyses identified an increased expression of genes involved in the ALT mechanism such as Pml, Rad50, Smc5, Fen1, FancA, Mus81, Sp110 and Sp100 in c-Myc/Suv39h1-null leukemias." (PMID 24202323, 2013). "In direct contrast, in leukemia, loss of H3K79me upon DOT1Li reduced H3K9ac and promoted H3K9me2 at target genic loci via a complex containing the deacetylase SIRT1 and H3K9 methyltransferase SUV39H1." (PMID 35733849, 2022). "Alternatively H3K79me2 was suggested to oppose H3K27me3 and H3K9me3 via SIRT1/SUV39H1 in leukemia." (PMID 35733849, 2022). "Although the interest in developing leukemia therapies by targeting H3K9 methyltransferases is increasing, the role of Suv39h1 and its associated H3K9me3 modification in MLL-r AML remains unclear." (PMID 33037410, 2020). "Suv39h1 knockdown with shSUV-a accelerated the progression of leukemia with an average of 20.5-day survival in shSUV-a group vs. 23-day in scramble established in parallel with shSUV-a, and 26-day survival in shSUV-b group vs. 30.5-day in its parallel scramble." (PMID 33037410, 2020).
leukemia (continued). "Moreover, immunoblot analyses of SUV-OE MLL-AF9 leukemia cells (P1 and P2 cells) showed that overexpression of Suv39h1 increased H3K9 trimethylation level in the whole BM cells isolated from secondary and tertiary recipient mice." (PMID 33037410, 2020). "Furthermore, restoration of Hoxb13 in SUV-OE AML cells accelerated the leukemia progression and increased the number of LSCs, suggesting Hoxb13 is a downstream effector of Suv39h1 in MA9 leukemia cells." (PMID 33037410, 2020). "However, the role of SUV39H1 via its-mediated repressive modification H3K9me3 in leukemogenesis/leukemia progression remains to be explored." (PMID 33037410, 2020). "Thus, the role of SUV39H1 in cancer may be context-dependent, and its specific roles in other subtypes of leukemia require further investigation." (PMID 33037410, 2020). "Thus, highly efficient DSB repair might be a potential mechanism for preventing chromosomal aberrations in c-Myc/Suv39h1-null leukemias." (PMID 24202323, 2013). "However, DSBs were markedly reduced in c-Myc/Suv39h1-null leukemias." (PMID 24202323, 2013). "Targeting SUV39H1 enhanced the persistence and antitumor effects of CAR T cells in lung and disseminated solid tumor models, as well as in leukemia and prostate cancer models." (PMID 40059829, 2025). "Suv39h1 overexpression increased leukemia latency and decreased the frequency of LSCs in MLL-r AML mouse models, while Suv39h1 knockdown accelerated disease progression with increased number of LSCs." (PMID 33037410, 2020). "Notably, prior studies have demonstrated that chaetocin binds to the C-terminal domain of HSP90α in leukemia, disrupting the function of several HSP90 client proteins and subsequently activating the proteasome pathway to degrade SUV39H1." (PMID 40227333, 2025). "For example, groups have found that disruption of SUV39H1, a histone methyltransferase important in Th2 commitment, improves CAR T cell persistence and endows them with a more “stem-like phenotype” in both leukemia and solid tumor models." (PMID 39199630, 2024). "Herein, we demonstrate that Suv39h1 is significantly down-regulated in AMLs and could function as a tumor suppressor in MLL-rearrangement induced leukemia by regulating Hoxb13 and Six1, as well as Hoxa/Meis1 downstream signature genes." (PMID 33037410, 2020). "Additionally, miR-142 targets ASH1L/KMT2H in leukemia and thyroid cancer, miR-675 regulates SUV39H2/KMT1B in liver cancer, miR-122 influences SUV39H1/KMT1A in hepatocellular carcinoma, and miR-101 modulates KMT6/EZH2 in non-small cell lung cancer (NSCLC), prostate, and renal cancers." (PMID 40761244, 2025). "Considering the non-direct effect of chaetocin on SUV39H1, we further explored whether direct suppression of Suv39h1 would accelerate leukemia progression by reducing the expression of Suv39h1 using shRNA-mediated knockdown." (PMID 33037410, 2020). "In addition, the expression level of SUV39H1 in stem/progenitor-enriched CD34+ AML cells was significantly lower than in normal cord blood CD34+ cells, which may either be due to the age effect or the combinative effects of age and leukemia." (PMID 33037410, 2020). "Notably, leukemias that arose in c-Myc/Suv39h1-null mice were chromosomally stable, demonstrating that reduced H3K9 trimethylation due to lack of Suv39h1 rather protects leukemic cells from the development of CIN." (PMID 24202323, 2013).
colon carcinoma (9 papers, 2019 to 2025). "Suv39H1 reduces cytotoxic T lymphocyte effector gene expression and causes colon cancer immune escape." (PMID 35619625, 2022). "Targeting SUV39H1 increased the expression of these effectors in CTLs, resulting in suppression of colon tumor growth." (PMID 40059829, 2025). "SUV39H1 was chosen as a therapeutic target since its expression is significantly higher in colon cancer cells and CTLs compared to normal cells." (PMID 39519018, 2024). "Overexpression of SUV39H1 is evidenced in bladder, liver, and colon cancer, melanoma, and clear cell renal carcinoma." (PMID 39519018, 2024). "A small molecule inhibitor of SUV39H1 has been developed, and it can suppress human colon tumor xenograft growth in vivo, which confirmed the therapeutic value of SUV39H1 in CRC." (PMID 35429301, 2022). "In human colon cancer (CRC), inhibition of SUV39H1 significantly increases the expression of granulozyme B, perforin, FasL, and IFN, inducing tumor cell apoptosis by enhancing immune surveillance and the killing effect of CTL." (PMID 38650654, 2024). "A study on verticillin A, a selective inhibitor of SUV39H1, reported its effect on the increased FAS transcription and apoptosis of colon carcinoma cells." (PMID 36064736, 2022). "SUV39H1 inhibition led to increased expression of granzyme B, perforin, FasL, and IFNγ, while a number of tumor-infiltrating CTLs remained unchanged in MC38 and CT26 colon tumor models." (PMID 39519018, 2024).
colorectal cancer (9 papers, 2006 to 2023). A primary or metastatic malignant neoplasm that affects the colon or rectum. "The methyltransferase of H3K9me3, SUV39H1, was up-regulated in colorectal cancer cells, and cancer cell migration was inhibited by the knockdown of SUV39H1." (PMID 36193203, 2022). "Suv39h1 activity controls cell migration in breast and colorectal carcinoma cells, while the depletion of suv39h2 induces apoptosis and cell death in ALL cells." (PMID 30213075, 2018). "HDAC1, HDAC5, HDAC7A, SIRT1, and SUV39H1 expression profiles were distinctive for colorectal cancers and normal colorectal mucosa." (PMID 16638127, 2006). "However, an oncogenic role of SUV39H1 has been reported in retioblastoma and clear cell renal cell carcinoma and up-regulation of SUV39H1 has been observed in several human cancers, such as colorectal cancer, bladder cancer, and hepatocellular carcinoma 108-112." (PMID 35069908, 2022). "It has been shown that there is a correlation between H3K9me3 expression and tumor progression in multiple cancer types (e.g., colorectal cancer) and that global H3K9 methylation upregulates tumorigenesis through the enzymatic activity of SUV39h1." (PMID 33898431, 2021). "In colorectal cancer cells, TIP60 also exerts an anti-inflammatory response by activating the expression of SUV39H1 and SETDB1, two histone H3K9 methyltransferases, which in turn repress the transcription of retrotransposon elements to contain STING/IRF7-mediated inflammation." (PMID 32626711, 2020).
hepatocellular carcinoma (8 papers, 2016 to 2025). A malignant tumor that arises from hepatocytes. "Elevated expression of Suv39h1, another histone methyltransferase which can catalyze H3K9me2, has been found to associate with higher incidence of hepatocellular carcinoma recurrence." (PMID 27144429, 2016). "The downregulation of this miRNA has been correlated to SUV39H1 upregulation in hepatocellular carcinoma cells." (PMID 35087589, 2022). "In hepatocellular carcinoma cells, knockdown of SUV39h1 expression has been shown to decrease H3K9me3 expression and disturb cell proliferation and sphere formation." (PMID 33898431, 2021). "Thus, we suggest that SUV39H1, which catalyzes histone H3K9me3 and has a higher Km value compared with other methyltransferases, is responsible for the susceptibility of H3K9me3 to SAM availability in hepatoma cells." (PMID 37166978, 2023). "However, whether SUV39H1 has an effect on hepatoma cells through the OXPHOS pathway remains to be explored." (PMID 38017386, 2023). "In addition, miR-122 is another regulator of SUV39H1 in hepatocellular carcinoma cells." (PMID 35087589, 2022). "SUV39H1 was increased by HBV infection and promoted the proliferation and migration of hepatoma cells." (PMID 38017386, 2023). "SUV39H1 is regulated by HBV infection and promotes the proliferation and migration of hepatoma cells by targeting OXPHOS pathway." (PMID 38017386, 2023). "In this study, we also confirmed that HBV infection could increase the expression of SUV39H1 promoting the proliferation and migration of HBV positive hepatoma cells." (PMID 38017386, 2023). "It suggested that SUV39H1 might promote metabolic reprogramming by regulating the OXPHOS pathway, thereby improving the proliferation and migration of hepatoma cells." (PMID 38017386, 2023).
lung carcinoma (8 papers, 2012 to 2025). "For instance, SUV39H1-mediated H3K9me3 can silence the tumor suppressor gene p16INK4a, promoting uncontrolled cell proliferation in acute myeloid leukemia and lung cancer cells." (PMID 40059829, 2025). "The results indicated that the expression of SUV39H1, a histone methyltransferase, was higher in lung cancer tissue than that in normal adjacent tissues, which opposed the expression trend of miR-744." (PMID 33472665, 2021). "A previous study reported that USP24 can stabilize MDM2 then decrease the Suv39h1 level resulting in lung cancer metastasis." (PMID 30911287, 2019). "We selected seven genes [4 unique genes (E2F6, TFDP1, SUV39H1, and HNRPD) for NSCLC and 3 genes (RBL1, IRF1, and HMGA1) for general events] for validation as diagnostic markers in lung cancer." (PMID 24564251, 2013). "Although in our blood-based qPCR, HNRPD and SUV39H1 are downregulated, they are reported to be upregulated in a mouse model of lung cancer, consistent with the tissue-based microarray analysis in our lung cancer samples." (PMID 24564251, 2013). "Our studies with modulation of Runx2 levels in lung cancer cells indicate that Runx2-mediated downregulation of BMP-3B levels is via interacting with methyltransrefase Suv39h1 and increasing histone H3K9 methylation status of the proximal promoter." (PMID 22537242, 2012). "A twofold increase in recruitment of Suv39h1 was observed in H1299-Runx2 cells compared to H1299-shRunx2 lung cancer cells." (PMID 22537242, 2012). "Our studies with Runx2 overexpression or knockdown in lung cancer cells indicate that Runx2-mediated downregulation of BMP-3B is via increasing histone H3K9 methylation status of the proximal promoter by interacting with methyltransrefase Suv39h1." (PMID 22537242, 2012). "Importantly, previous studies demonstrated that SUV39H1 and SETDB1 are highly expressed in lung cancer, and the dysregulation of SUV39H1 and SETDB1 accelerates the development of lung cancer, suggesting that aberrant H3K9 methylation plays a critical role in lung carcinogenesis." (PMID 30054425, 2018). "Furthermore, the tumor suppressor protein RB1 is downregulated in lung cancer and may inhibit SUV39H1." (PMID 24564251, 2013). "Therefore, SUV39H1 expression differs in lung cancer tissue and blood samples." (PMID 24564251, 2013). "Taken together, these results show that the recruitment of Runx2 and Suv39h1 on the BMP-3B proximal promoter sequences resulted in increased H3K9 methylation status and consequently downregulation of BMP-3B expression in lung cancer cells." (PMID 22537242, 2012). "Both SUV39H1 and SUV39H2 were reported to catalyze the formation of H3K9me2 and H3K9me3, and also participated the cell cycle regulation in a variety of cells, including the epidermal stem and progenitor cells and lung cancer cells." (PMID 37306883, 2023).
melanoma (8 papers, 2011 to 2022). A malignant, usually aggressive tumor composed of atypical, neoplastic melanocytes. "Formation of various cancer types including rhabdomyosarcoma and melanoma are sensitive to the loss of SUV39H1." (PMID 30466474, 2018). "Conversely, depletion of SUV39H1 in melanoma cells leads to RB1 activation and reduced E2F1 transcriptional activity, inhibiting melanoma development." (PMID 35163453, 2022). "Consistent with this working model, signatures from scRNAseq CD8+ T cells from melanoma patients that respond to immune checkpoint blockers correlated strongly with the transcriptomic signature of PD-1-treated Suv39h1-KO CD8+ T cells." (PMID 35768432, 2022). "In differentiated melanoma cells, silencing SUV39H1 or the other H3K9 methyltransferase, G9A, can elevate their self-renewal capabilities." (PMID 30466474, 2018). "Reciprocally, the PD-1-treated Suv39h1-KO signature was enriched in responding patients, indicating that this signature could potentially be used as biomarker of response in melanoma patients." (PMID 35768432, 2022). "To interrogate the role of Suv39h1 in T cell responses to cancer, we used a partially anti-PD-1 blockade resistant melanoma model, B16F10-OVA (in which the tumor cells express the surrogate tumor-antigen ovalbumin) grafted in WT or Suv39h1-KO mice." (PMID 35768432, 2022). "Overexpression of either SET domain bifurcated histone lysine methyltransferase 1 (SETDB1) or suppressor of variegation 3–9 homolog 1 (SUV39H1), both enzymes methylating histone H3 on lysine 9 (H3K9), significantly accelerates melanoma formation." (PMID 35163453, 2022). "SUV39H1/DNMT3A-dependent methylation of the RB1 promoter stimulates PIN1 expression and melanoma development." (PMID 33234142, 2020). "The other two histone methyltransferases (HMTs), SETDB1 and Histone-lysine N-methyltransferase SUV39H1 (SUV39H1), also cooperate with BRAF V600E to accelerate the incidence and severity of melanoma development in fish." (PMID 30544544, 2018). "Authors show here that the histone lysine methyltransferase Suv39h1 controls the transcriptional programs that determine the functionality of CD8 + T cells and Suv39h1 inhibition may potentiate anti-PD-1 therapy of melanomas." (PMID 35768432, 2022).
acute myeloid leukemia (6 papers, 2015 to 2025). Acute myeloid leukemia (AML) is a group of neoplasms arising from precursor cells committed to the myeloid cell-line differentiation. "Previous research revealed that chaetocin exerts a dual mechanism by directly inhibiting SUV39H1 and indirectly affecting it via ROS production in acute myeloid leukemia cells." (PMID 40059829, 2025). "SUV39H1 inhibition is sufficient for re-expression of the silenced tumor suppressor genes CDKN2B and CDH1 marked by H3K9me3 in acute myeloid leukemia." (PMID 26840455, 2016).
B-cell lymphomas (6 papers, 2013 to 2025). "Loss of SUV39H1 in a myc-driven model of murine B cell lymphomas led to faster onset of disease, whereas SUV39H1 wild-type mice displayed increased levels of senescence and growth arrest." (PMID 23705022, 2013). "These double null or Suv39h1-null mice showed an increased predisposition to B cell lymphomas with hyperdiploid karyotypes, suggesting that lack of pericentromeric heterochromatin might increase genomic instability by impairing chromosome segregation." (PMID 27924426, 2016).
prostate carcinoma (6 papers, 2017 to 2025). A carcinoma that arises from epithelial cells of the prostate gland. "Suv39H1 plays a vital role in the proliferation and migration of prostate cancer cells." (PMID 35619625, 2022). "To better understand the impact of SUV39H1 on the epigenetic regulation of cell proliferation and migration, we compared the genomic DNA methylation profile in SUV39H1 knockout (KO) and wild-type (WT) prostate cancer cells." (PMID 33066102, 2020).
rhabdomyosarcoma (6 papers, 2013 to 2019). A rare aggressive malignant mesenchymal neoplasm arising from skeletal muscle. "Recently, it was found that overexpression of the KMT1, SUV39H1 in zebrafish can suppresses a rhabdomyosarcoma model produced by KRASG12D overexpression." (PMID 25429045, 2014). "Here, we describe an overexpression screen of chromatin-modifying factors that revealed SUV39H1 suppresses the onset of rhabdomyosarcoma formation in zebrafish." (PMID 23705022, 2013). "The present study has shown that Suv39h1 as a tumor suppressor of reducing rhabdomyosarcoma formation in zebrafish, which could be used for cancer therapy." (PMID 27916793, 2016).